ALDH1B1 (aldehyde dehydrogenase 1 family member B1)
Diseases named in the same sentence as ALDH1B1 in open-access papers (continued):
Sharing a sentence is not in itself a finding about the gene and the disease.
cancer (continued). "ALDH1B1, an aldehyde dehydrogenase, is a cancer stem cell (CSC) marker that is required for carcinogenesis via upregulation of the β-catenin pathway." (PMID 34769507, 2021). "ALDH1A2 is expressed at very low level in all types of cancer, whereas ALDH1B1, ALDH3B1, and ALDH5A1 are expressed at medium level universally, implying a ubiquitous role of these isoforms." (PMID 30220009, 2019). "Taken together, our data indicate that ALDH1B1 played a crucial role in OS cell proliferation, at least in part by modulating cancer stem function." (PMID 29416787, 2018). "Consistent with the result confirmed by above studies in other cancers, we firstly confirmed that ALDH1B1 was significantly over-expressed in OS tissues and cell lines." (PMID 29416787, 2018). "Future studies to understand the molecular mechanisms of ALDH1B1 involved in cancer progression will be required." (PMID 29416787, 2018). "For example, ALDH1A2, ALDH2, ALDH3A2 and ALDH9A1 were downregulated in all tumors among the 5 cancer types, whereas ALDH1B1, ALDH1L2 and ALDH18A1 were most upregulated in tumor parts." (PMID 29426835, 2018). "Suppression of ALDH1B1 expression by shRNA reduced spheroid formation by SW480 cells in a three-dimensional cancer cell culture and reduced tumor growth by SW480 cells in an in vivo xenograft model." (PMID 25950950, 2015). "Both genetic depletion and pharmacological inhibition of ALDH1B1 significantly reduced metastatic burden and extended median survival in nude mouse models, highlighting its potential to suppress metastatic recurrence in post-operative cancer patients." (PMID 41390768, 2025). "Given its potential as a cancer marker, targeting ALDH1B1 could be a promising strategy to inhibit cancer progression." (PMID 39438459, 2024). "High ALDH1B1 expression has been correlated with increased migration, chemoresistance, altered cell cycle regulation, and an enhanced DNA damage response in CRC cells, underlining its multifaceted role in cancer advancement and therapeutic resistance." (PMID 38673727, 2024). "The ALDH1B1 isoform has not been extensively studied, however novel data support its association with cancer development and the CSC phenotype." (PMID 36676146, 2023). "Comparing HCC in the choline deficient model and choline supplemented model, significant methylation differences were seen in 11 genes previously associated with cancer (hypermethylation of TRAP1, SLC38A3, CHRM1, EDN2, and PROX1; hypomethylation of ALDH1B1, FTCD, FASTKD2, FAM96A, and ARHGAP15)." (PMID 36474183, 2022). "We examined the effect of ALDH1B1 silencing on the protein expressions of cancer stem cell markers." (PMID 29416787, 2018). "The present study also showed that ALDH1B1 silencing could suppress the protein expressions of cancer stem cell markers." (PMID 29416787, 2018). "However, only one dataset showed the significant fold change (2.610, p = 6.87E-4) of ALDH1B1 mRNA levels between cancer and normal tissue." (PMID 27015121, 2016). "Furthermore, ALDH1B1 knockdown could enhance the cytotoxic effect of chemotherapy (doxorubicin) through regulating cancer stem cells in OS cells." (PMID 29416787, 2018). "In contrast, ALDH1B1, aldehyde dehydrogenase 1 family member L2 (ALDH1L2), and 18 family member A1 (ALDH18A1) are upregulated in most cancers." (PMID 40923024, 2025). "This linkage positions ALDH1B1 as a potential CSC marker in CRC, further implicating it in cancer aggressiveness and resistance to therapy." (PMID 38673727, 2024). "Indeed, ALDH1B1 antioxidant activity, its association with the metabolism of RA, its potential to upregulate the DNA damage response cascade, and its involvement with cancer and stem-related pathways, such as Wnt/β-Catenin, Notch, and PI3K/Akt, can provide several advantages to cancer cells." (PMID 36676146, 2023). "Gene expression analysis showed that epithelial cells in type 3 TETs expressed high levels of cancer stem cell (CSC)-related markers (NOTCH2, CD24, ALDH1B1 and PROM1)." (PMID 36115836, 2022).
cancer (continued). "Several isoforms of the ALDH1 family (ALDH1A1, ALDH1A2, ALDH1A3, ALDH1B1, ALDH1L1, and ALDH1L2) are used as cancer stem cell markers in a variety of cancers." (PMID 34680942, 2021). "We demonstrated that ALDH1B1 induced EMT in HT29 cells and cancer stem-like cells (through the upregulation of ZEB1), resulting in the downregulation of E-cadherin." (PMID 33419031, 2021). "In detail, ALDH9H1, ALDH18A1, ALDH3A2, ALDH1A1, ALDH1B1 and ALDH2 were expressed higher than other ALDH family genes in all cancers." (PMID 34670872, 2021). "Recent studies have revealed that ALDH1B1, another number of ALDH1 family, plays a vital role in several human cancers." (PMID 29416787, 2018). "ALDH1B1, a mitochondrial ALDH, is another promising good prognostic marker for cancer, sharing 65% homology in peptide sequence with cytosolic ALDH1A1 in humans." (PMID 28792511, 2017). "Aldehyde dehydrogenase (ALDH1B1, ALDH2, ALDH3B1, ALDH3B2, ALDH7A1 and ALDH9A1) were involved in the resistance against cyclophosphamide/carboplatin in cancer chemotherapy." (PMID 28225065, 2017). "Although ALDH1B1 has not been extensively studied in other types of cancer, the experimental evidence available so far supports its emergence as a promising candidate marker of CSCs." (PMID 36676146, 2023). "Our data raise an intriguing possibility that ALDH1B1 may in fact be able to sustain the CSC phenotype and promote growth of cancer cells by protecting cells from DNA damage." (PMID 35805102, 2022). "ALDH1B1 has been reported to involve in many kinds of human cancers and functions as an oncogene, but the role of ALDH1B1 in OS has not been investigated comprehensively." (PMID 29416787, 2018). "However, no cancer-type specific expression preference of ALDH1A2, ALDH1B1, ALDH3B1, and ALDH5A1 has been observed." (PMID 30220009, 2019).
tumor (26 papers, 2013 to 2025). "We established A549 cells with ALDH6A1 or ALDH9A1 depletion and found that ALDH9A1 depletion increased tumor cell death in confining pores, though its effect was weaker than that of ALDH1B1 ablation." (PMID 41390768, 2025). "Immunofluorescence analysis of mouse lung tissues harvested 24 h after tail vein injection showed that ALDH1B1 depletion significantly increased 4-HNE levels in tumor cells confined within lung capillaries." (PMID 41390768, 2025). "The upregulation of ALDH1B1 enhances aldehyde detoxification, which suppresses ferroptosis and promotes tumor cell survival during migration through the capillaries, thereby facilitating metastasis." (PMID 41390768, 2025). "Collectively, these results demonstrate that the expression of ALDH1B1 is increased in tumor cells during confined migration in response to compressive force." (PMID 41390768, 2025). "Here, through an in vivo CRISPR screen targeting metabolic enzymes, we identify aldehyde dehydrogenase 1 family member B1 (ALDH1B1) as essential for tumor cell survival in confining capillaries." (PMID 41390768, 2025). "TUNEL assay on dissected lung tissues showed that ALDH1B1 depletion increased tumor cell death in lung capillaries." (PMID 41390768, 2025). "Our study mainly focuses on mechanical compression, demonstrating that the CSK23-IKKβ-ALDH1B1 pathway is critical for tumor cell adaptation to compressive forces, enabling their survival in constricted capillaries." (PMID 41390768, 2025). "Bioluminescence imaging of the mice showed that ALDH1B1 depletion accelerated the diminishment of bioluminescence signals of tumor cells in brain 7 days after inoculation, and dampened brain metastasis of the cells 63 days after inoculation." (PMID 41390768, 2025). "ALDH1B1, a member of the aldehyde dehydrogenase family, has emerged as a pivotal regulator in tumor biology." (PMID 41390768, 2025). "Collectively, these results suggest that ALDH1B1 plays a dual protective role in confined tumor cells by suppressing both ferroptosis and apoptosis, with its anti-ferroptotic effect being mechanistically dominant." (PMID 41390768, 2025). "Here, the authors discover that compression force-induced CSK23-mediated NF-κB activation regulates ALDH1B1 expression, ultimately modulating ferroptosis and tumor cell survival in confining capillaries." (PMID 41390768, 2025). "Mechanistically, in response to compressive force, CSK23 interacts with and phosphorylates IKKβ at S177/181 in confined tumor cells, thereby activating NF-κB pathway to upregulate ALDH1B1 expression." (PMID 41390768, 2025). "Confinement significantly increased lipid peroxidation in tumor cells, and depletion of ALDH1B1 further exacerbated these effects." (PMID 41390768, 2025). "At 24 h post-injection, the ALDH1B1-depleted group showed accelerated diminishment of bioluminescence signals from tumor cells in lung tissues." (PMID 41390768, 2025). "To investigate how ALDH1B1 is regulated in tumor cells during confined migration, we examined ALDH1B1 expression in confined cells." (PMID 41390768, 2025). "Immunofluorescence analysis indicated that both ALDH1B1 expression levels and nuclear RelA levels were increased in tumor cells constrained in lung capillaries, compared to tumor cells outside capillaries." (PMID 41390768, 2025). "Collectively, among ALDH isoforms, ALDH1B1 is identified as the primary regulator governing tumor cell survival under spatial confinement." (PMID 41390768, 2025). "Negative regulation of ALDH1B1 by microRNA-761 in osteosarcoma cells suppresses tumor cell proliferation by regulating TGF-β signaling and cell adhesion." (PMID 34769507, 2021). "Further studies are needed to illuminate the interaction between ALDH1B1 and oncogenic function involved in modulating tumor cell survival." (PMID 29416787, 2018). "The function of ALDH1B1 was further elucidated in vivo by subcutaneous tumor transplantation with the control vector, NC shRNA, ALDH1B1 shRNA." (PMID 29416787, 2018).
tumor (continued). "To evaluate the effect of ALDH1B1 knockdown on tumor growth, we used an in vitro three-dimensional culture system and an in vivo xenograft model." (PMID 25950950, 2015). "In a 3-dimensional spheroid growth model and a nude mouse xenograft tumor model, shRNA-induced suppression of ALDH1B1 expression decreased the number and size of spheroids formed in vitro and the size of xenograft tumors formed in vivo by SW 480 cells." (PMID 25950950, 2015). "We used the SW480 cell line to examine the effect of suppressing ALDH1B1 expression on tumor growth." (PMID 25950950, 2015). "Additionally, PIEZO1 depletion inhibited ALDH1B1 expression in tumor cells confined within lung capillaries." (PMID 41390768, 2025). "Notably, nuclear RelA levels showed a strong positive correlation with ALDH1B1 expression in confined tumor cells." (PMID 41390768, 2025). "To investigate how ALDH1B1 promotes tumor cell survival in confining spaces, we depleted ALDH1B1 in A549, H1299 cells, or H460 cells and rescued the cells with wild-type ALDH1B1 (WT) or ALDH1B1 enzymatic-dead (ED) mutant, which indeed had much lower activity than WT." (PMID 41390768, 2025). "For comparison, all three tumor types showed robust Aldh1b1 expression." (PMID 39548190, 2025). "Additionally, capillary-confined tumor cells from patients with metastatic recurrence showed elevated ALDH1B1 expression and reduced 4-HNE accumulation compared to the cells from non-recurrent cases." (PMID 41390768, 2025). "Here, we demonstrate that in response to compressive force, NF-κB pathway is activated to upregulate ALDH1B1 expression, which suppresses tumor cell ferroptosis during migration in confining capillaries by detoxifying aldehydes, thereby promoting their distant metastasis." (PMID 41390768, 2025). "To test the hypothesis, we applied direct compressive force to tumor cells and examined ALDH1B1 expression, which showed that the mRNA and protein levels of ALDH1B1 were upregulated in the cells after compression in a dose and time-dependent manner." (PMID 41390768, 2025). "However, compared to its effect on ferroptosis, ALDH1B1 depletion had a much weaker influence on the apoptosis of confined tumor cells." (PMID 41390768, 2025). "To investigate whether ALDH1B1 promotes tumor cell survival in confining spaces, we simulated confinement scenario in vitro by adopting a transwell chamber with 8 μm pores." (PMID 41390768, 2025). "ALDH1B1 was identified to be required for tumor cell survival in confining capillaries." (PMID 41390768, 2025). "Immunofluorescence analysis showed that ALDH1B1 depletion led to a twofold reduction in tumor cells retained within capillaries and a fivefold decrease in extravasated tumor cells, suggesting that ALDH1B1 likely also contributes to the survival of tumor cells during extravasation." (PMID 41390768, 2025). "Meanwhile, downregulation of ALDH1B1 inhibited the tumor growth in vivo." (PMID 29416787, 2018). "To confirm our speculation, we investigated whether ALDH1B1 facilitate the tumor growth by regulating stemness of OS in a subsequent mechanistic experiment." (PMID 29416787, 2018). "In addition, the silence of ALDH1B1 inhibited the tumor growth in vivo, probably by inhibiting cell proliferation in OS." (PMID 29416787, 2018). "Taken together, our founding suggested that ALDH1B1 contributes to OS tumor progression and drug resistance, which may represent a novel prognostic marker and potential therapeutic target for OS patients." (PMID 29416787, 2018). "We found that the silencing of ALDH1B1 inhibited the tumor growth of OS." (PMID 29416787, 2018). "However, the expression of ALDH1B1 were closely related with tumor TNM stage (P=0.027), tumor size (P=0.001), tumor metastasis (P=0.006) and patients survival (P= 0.001)." (PMID 29416787, 2018). "Furthermore, tumor volume in a xenograft model was reduced in tumors derived from ALDH1B1 knockdown cells than in those derived from scramble control cells." (PMID 25950950, 2015).
tumor (continued). "This may explain the decrease in tumorigenicity observed in the ALDH1B1 knockdown cells in our in vitro and in vivo tumor formation assays." (PMID 25950950, 2015). "SL exposure also induced changes in the expression of genes involved in metabolic functions in tumor and stem cells (ALDH1B1, ABCB1, SLC3A2, SLC44A2, SLC31A2, SLC7A11, CYP24A1, PTGS2/COX2, PPRC1), cytokines (CCL3L3, GDF15) and growth and differentiation factors (PGF, TGFBR11 and FOXD1)." (PMID 24742967, 2014). "We propose targeting circulating tumor cells during early dissemination-a phase characterized by limited population size and unique metabolic dependencies, which may enable effective metastasis blockade via transient, submaximal ALDH1B1 inhibition." (PMID 41390768, 2025). "In addition, we also investigated whether ALDH1B1 regulates tumor cell survival during extravasation through endothelial gaps." (PMID 41390768, 2025). "However, the functional significance of ALDH1B1 in confined migration-a critical mode of in vivo tumor cell locomotion-and its mechanistic role in metastasis remain unclear." (PMID 41390768, 2025). "Importantly, we depleted IKKβ in tumor cells and observed that depletion of IKKβ suppressed the compression-induced phosphorylation and degradation of IκBα as well as ALDH1B1 expression." (PMID 41390768, 2025). "Moreover, the survival and the migratory capability of RelA-depleted cells were also greatly recovered by ALDH1B1 overexpression, whereas RelA depletion showed no significant impact on lipid peroxidation or survival in unconfined tumor cells." (PMID 41390768, 2025). "However, whether the CSK23-IKKβ-ALDH1B1 pathway is also critical for tumor cell adaptation to fluid shear stress within capillaries requires further investigation." (PMID 41390768, 2025). "Hence, ALDH1B1 loss increases acetaldehyde levels and DNA damage that interacts with dMMR to accelerate colonic, but not small intestinal, tumour formation." (PMID 37395714, 2023). "Moreover, ALDH1B1 silencing could suppress the proliferation, migration, invasion in vitro and inhibit the growth of xenograft tumor and of OS cells in vivo." (PMID 29416787, 2018). "In addition, the present study provides mechanistic insights into the means by which ALDH1B1 may promote tumor formation, i.e., by modulating the Wnt/β-catenin, Notch, and PI3K/Akt signaling pathways." (PMID 25950950, 2015). "We also examined the survival of tumor cells in polydimethylsiloxane (PDMS) microchannels and found that ALDH1B1 depletion increased tumor cell death in these channels." (PMID 41390768, 2025). "Although upregulated EIF4E is well characterized in promoting tumor growth, we provide evidence that EIF4E has a tumor suppressor function in HT-1080 and Calu-1 cells as it binds to ALDH1B1 to induce ferroptosis." (PMID 36274088, 2022). "Compared with its effect on the control group, IKE-mediated tumor suppression was weakened in the EIF4E-knockdown group, but enhanced in the ALDH1B1-knockdown group." (PMID 36274088, 2022). "4HNE-mediated tumor suppression was reduced in the EIF4E-knockdown group, but enhanced in the ALDH1B1-knockdown group." (PMID 36274088, 2022). "The ALDH isoform ALDH1B1 is suggested to contribute to CRC growth, and studies have shown that suppression of ALDH1B1 expression in SW480 CRC cells inhibits spheroid formation in vitro and tumor formation in xenograft models in vivo." (PMID 34503214, 2021). "The current study provided novel insights into the tumor-suppressive mechanism of AMBRA1 and the post-translational modification of ALDH1B1, a CSC marker." (PMID 34769507, 2021). "The oncogenic components, namely, ALDH1B1, ALDH1L2, CHSY1, CSGALNACT2, and GPX8, were progressively upregulated in more aggressive tumors, while the tumor suppressor hubs FBP1 and HPGD were downregulated as tumor aggressiveness increased." (PMID 40626022, 2025).